SOD2 (superoxide dismutase 2)
Diseases named in the same sentence as SOD2 in open-access papers (continued):
Sharing a sentence is not in itself a finding about the gene and the disease.
tumor (continued). "Moreover, some researchers claim that SOD2 undergoes a functional shift, transitioning from a tumor initiation suppressor to an actual tumor promoter, contributing to the progression toward more malignant phenotypes once the disease is established." (PMID 38891864, 2024). "SOD2 is involved in tumor progression through a variety of mechanisms." (PMID 39871949, 2024). "Furthermore, SOD2 can play dual roles in tumor suppression or metastatic disease progression at initial stages and later stages of tumor progression, respectively." (PMID 37827291, 2023). "In present study, we demonstrate that IGFBP1 is upregulated in tumor cells during confined migration, which promotes ROS scavenging in mitochondria by activating SOD2, mitochondrial Mn‐SOD, thereby supporting the survival of tumor cells during confined migration." (PMID 37296072, 2023). "The obtained data demonstrated NB’s potential to suppress SOD2 to control tumor growth." (PMID 37891871, 2023). "Moreover, the upregulation of SOD2 contributes to anoikis resistance, prolonging tumor cell survival." (PMID 37827291, 2023). "Moreover, the SOD2 gene was expressed at higher levels in metastatic sites than in primary tumor and normal tissues." (PMID 37891871, 2023). "This could contribute, at least in part, to explain the contradictory results found concerning the dichotomous role of SOD2 in cancer, to which a tumor suppression or a tumor promotion function has been attributed." (PMID 37533102, 2023). "Enhanced SOD2 attenuates mitochondrial reactive oxygen species (ROS) accumulation in confined cells, which supports tumor cell survival in blood vessels of lung tissues, thereby accelerating tumor metastasis in mice." (PMID 37296072, 2023). "In addition, SOD2 has a protective role against radiotherapy; it increases the malignant properties of tumor cells, such as invasion, migration, and anchorage-independent growth." (PMID 37108069, 2023). "Moreover, SOD2 is a putative tumor-suppressor gene and its epigenetic silencing results in cancer cell proliferation." (PMID 37638880, 2023). "Xenografted PDAC cells overexpressing SOD2 exhibited rapid tumor growth in vivo." (PMID 37891871, 2023). "Second, our data may contribute to reconcile apparently discordant findings of the literature regarding (i) the pro- and anti-migratory properties of ROS in cancer cells or (ii) the tumor-promoting or tumor-suppressive effect of SOD2." (PMID 37533102, 2023). "Indeed, an increasing number of studies have demonstrated the multiple roles of SOD2 in cancer progression, metastasis, and tumor inhibition in different types of cancer and tumor stages." (PMID 37827291, 2023). "Moreover, we examined the antiferroptotic role of SOD2 by comparing the efficacy of this analog between scramble and SOD2-suppressed tumor xenografts." (PMID 37175412, 2023). "Increased tumor growth inhibition was observed in SOD2-suppressed mice xenografts treated with IKE." (PMID 37175412, 2023). "SOD2 is traditionally regarded as a tumor suppressor in early studies." (PMID 37296072, 2023). "Hypoxia in the tumor environment may drive the activation of the p38-Hur-SOD2 axis, resulting in a decrease in the sensitivity of the tumor to anoikis." (PMID 37179119, 2023). "Finally, NB treatment to SOD2-overexpressing PDAC xenografts resulted in significant inhibition of tumor growth and metastasis." (PMID 37891871, 2023). "Findings from various studies strongly support our hypothesis that the activation of CD44 by its major ligand hyaluronan (HA) activates the transcription of SOD2 to promote tumor cell invasion/metastasis." (PMID 35164076, 2022). "Our study found seven downstream factors that may be associated with chemoresistance, LTF, SOD2, STAT1, CDKN2A, CD81, RAC1, and NDRG1 and five factors that may be associated with tumor development, CCN1, DCTN3, MUC1, H1-5, and SLC1A5." (PMID 35421932, 2022).
tumor (continued). "In addition, the expression of PRDX2 and PRDX5 in the GPx2 KD tumor was increased by 1.3-fold (logFC = 0.4) and catalase by 1.2-fold (logFC = 0.27), whereas the expression of SOD2 was unchanged." (PMID 35193955, 2022). "We envision that the robustness of SOD2 could make of this protein an ideal circulating tumor biomarker for cytotoxic cancer therapies." (PMID 36010852, 2022). "The preceding suggests that loss of SOD-2 expression could be a tumor-initiating phenotype and that SOD-2 as tumor suppressor function is primarily related to its role as an O2 scavenger throughout tumorigenesis." (PMID 35368886, 2022). "However, our current data suggest that the large increase in SOD2 levels measured by ELISA both in vitro (in tumor cells) and in vivo (on BC patients) would originate mostly from the mitochondrial form liberated upon cell death rather than from secretion." (PMID 36010852, 2022). "SOD2 regulates mitochondrial superoxide scavenger and can either suppress or promote tumor growth." (PMID 36430822, 2022). "Here, we chose to functionally validate SOD2 as a tumor biomarker." (PMID 36010852, 2022). "The ability to use SOD2 to modify the cellular redox environment can help with the identification of redox-responsive signaling events that stimulate malignancy, such as invasion, migration, and prolonged tumor cell survival." (PMID 35164076, 2022). "SOD2 was overexpressed in metastatic tumor lesions and aggressive tumor cell lines." (PMID 35164076, 2022). "By the same token, the question arises in terms of whether the polymorphism of the NRF2, GSTM3, SOD2 and GPX3 genes can affect the tumor progression, the prognosis of patients with testicular GCT and eventually the response to systemic chemotherapy." (PMID 35205816, 2022). "Importantly, inhibition of SOD2 leads to decreased spheroid formation, suggesting potential combination strategies in tumor treatment to overcome resistance." (PMID 34681918, 2021). "SOD2 is a key enzyme with a dual role in tumorigenesis and tumor progression in multiple cancers." (PMID 34319007, 2021). "Nonetheless, it has been suggested that SOD2 expression in human cancer might be stage- and/or tumor-type-dependent." (PMID 34948180, 2021). "We evaluated the effect of SOD2 on Tf-D-HKC8 peptide-mediated tumor suppression." (PMID 33423158, 2021). "However, in other cancer types such as lung and prostate, SOD2 levels have been found suppressed, hence, suggesting that the regulation of intracellular antioxidants depends on the primary tumor." (PMID 34777681, 2021). "Furthermore, Phy strongly suppressed the expression levels of Nrf2 and its downstream proteins including HO-1, SOD-1 and SOD-2 in the tumour lysis of MCF-7-xenografted in BALB/c nude mice." (PMID 33715588, 2021). "However, when this occurs in cancer cells or tumor tissue, SOD2 is a two-edged sword because antioxidant excess can induce the survival of damaged cells and then promote their proliferation and prompt the survival of neoplastic cells." (PMID 34062984, 2021). "Moreover, SIRT3/SOD2 signaling pathway has been shown to be involved in integrin-induced ROS generation in platelets and tumor cells." (PMID 34616362, 2021). "In conclusion, SOD1-deficient mice and tissue-specific SOD2-deficiet mice were useful model mice for an aging study without tumor progression." (PMID 33805584, 2021). "SOD2 overexpression also promotes tumor growth and metastasis in OCCCs." (PMID 33525614, 2021). "On the other side, an increased SOD2 activity may lead to tumor progression by modulating the levels of H2O2 in mitochondria." (PMID 32111081, 2020). "Additionally, miR-146 increased tumor cell (CAOV3 cells) sensitivity to paclitaxel by downregulating the expression of superoxide dismutase 2 (SOD2), although it was ineffective in regulating the sensitivity to cisplatin." (PMID 31936634, 2020). "In addition, NF-κB is known to participate actively in the regulation of SOD2 expression in tumor cells." (PMID 32585852, 2020).
tumor (continued). "SOD2 plays crucial roles in the tumor-initiating features that are related to TMZ resistance." (PMID 31629402, 2019). "SOD2 has both tumor promoting and suppressing functions in cancer." (PMID 31870275, 2019). "In addition, SOD2 mediated cell invasion induced by extracellular factors, such as IL-6 and SULF2, suggesting that SOD2 plays an essential role in cell invasion induced in response to tumor microenvironment changes." (PMID 30755594, 2019). "Therefore, SOD2 is a potential target for preventing cancer cell invasion following radiotherapy and suppressing tumor progression under diverse conditions." (PMID 30755594, 2019). "Indeed, a protective role of SOD2 against tumor progression in transformed cell lines has been reported." (PMID 29774090, 2018). "However, the different roles played by SOD2 in cancer progression, metastasis and tumour inhibition, must be carefully assessed when considering SOD2 as a potential target." (PMID 29914559, 2018). "Manganese superoxide dismutase (MnSOD or SOD2) are highly expressed in different neoplasia." (PMID 29774090, 2018). "Interestingly and in contrast to the ‘undead’ AiP model, removing intracellular ROS by misexpression of intracellular Catalase, SOD1 and SOD2 also strongly suppressed tumor growth." (PMID 28853394, 2017). "For example, immediate activation of SOD2 may be required as cells detach from the primary tumor, when matrix detachment initiates rapid redox stress and nutrient deprivation." (PMID 29099803, 2017). "Interestingly, it was subsequently shown that changes in SOD2 expression and activity are tumor type-dependent, with some cancers displaying increased SOD2 levels compared to their normal tissues of origin." (PMID 29099803, 2017). "In addition, we and others have demonstrated that increased SOD2 activity also shifts the redox balance towards a higher cellular steady-state H2O2 status in tumor cells." (PMID 29099803, 2017). "However, during metastatic progression, SOD2 levels appear to increase, as seen in metastatic tumor lesions and highly aggressive tumor cell lines." (PMID 29099803, 2017). "Moreover, radiation-induced SOD2 overexpression improves HT-29 tumor cell radiosensitivity while exerting radioprotection effects on normal CCD 841 CoN cells." (PMID 27999194, 2017). "We first measured the SOD2 expression from the tumor tissues, including mRNA and protein level." (PMID 28977893, 2017). "In our study, in both types of HCCs, NASH-related and HCV+, two downstream proteins of Nrf2, namely, NQO1 and SOD2, which participate in ROS elimination, were found induced, indicating that Nrf2 plays an important role in adaptation to oxidative stress in the tumor." (PMID 28218651, 2017). "The results indicate that BA/CDM combination could synergistically inhibit EBV replication and suppress tumor growth, SOD2 knockdown mimics this effect, and SOD2 overexpression diminishes this inhibition effect, worsening the problem." (PMID 28977893, 2017). "SOD2 inhibits tumor proliferation and metastasis and improves the radiosensitivity of tumor cells." (PMID 27999194, 2017). "The underlying genetic landscape of tumors, including expression of oncogenes or tumor suppressors, may also impact SOD2 transcription." (PMID 29099803, 2017).
tumor (continued). "A loss of SOD2 expression is frequently observed during tumor initiation, such as early tumor lesions and non-metastatic cancer cell lines." (PMID 29099803, 2017). "Overexpression of SOD2 within the tumor cells is believed to produce excessive hydrogen peroxide that disrupts redox balance and aggravates the oxidative damage, in turn, suppressing tumor cell proliferation and promoting apoptosis of tumor cells." (PMID 27999194, 2017). "Furthermore, we investigated the expression of Nrf2 and of redox-related genes (GCL-C, GCL-M, GR and SOD2) in normal and tumor tissue of control and T/H mice." (PMID 26595676, 2016). "Long-term treatment with nelfinavir reduced protein levels of SOD1, SOD2 and catalase in tumor cells, and while it was well established that detoxifying enzymes can be activated and upregulated by ROS, their decrease in oxidative stress condition is not completely understood." (PMID 27280849, 2016). "However, a lower SOD2 activity is detected in tumor cells from many reports, while some studies also reports an elevated SOD2 level in tumor cell lines." (PMID 27023612, 2016). "Furthermore, low SOD2 protein expression correlates with worse prognosis for patients with large tumors (tumor size > 5cm)." (PMID 27221200, 2016). "Moreover, down-regulation of SOD2 protein expression is correlated with multiple tumors, tumor embolus, cancer recurrence, and more advanced tumor stages as defined by the TNM and BCLC staging systems." (PMID 27221200, 2016). "Thus the role of SOD2 appears to be tumor-suppressive or -promoting, dependent on tissue types and/or disease stages." (PMID 27221200, 2016). "The cancer cell might have reduced SOD2 activity at the tumor early stage but switch to higher SOD2 activity later during cancer progression." (PMID 27023612, 2016). "However, in tumor tissues, SOD2 protein expression showed considerably variations, ranging from negative, low, moderate to high IHC staining." (PMID 27221200, 2016). "Conversely, it can be anticipated that SOD2 up-regulation may reduce the level of ROS in tumor cells." (PMID 25745358, 2015). "In addition, we also showed that SOD-induced H2O2 production promoted tumor cell invasion; while si-SOD2 and PEG-CAT treatment inhibits these effects." (PMID 26439801, 2015). "We can, therefore, speculate that increased SOD2 levels may confer an adaptive advantage to tumor cells favoring disease establishment and progression." (PMID 25745358, 2015). "However, there are also many reports that SOD2 has characteristics of tumor suppressor and can inhibit cancer development and progression." (PMID 26439801, 2015). "The SOD2 gene expression level was decreased in tumor cells and increased in aggressive tumor." (PMID 24690091, 2014). "SOD2 involvement in tumour pathogenesis and progression is controversial." (PMID 24736663, 2014). "Interestingly, Superoxide dismutase (SOD2), a probable tumor suppressor responsible for the destruction of superoxide free radicals, displayed a 15.9-fold increase in expression following TIMELESS knockdown." (PMID 24161199, 2013). "FAM60A is also implicated in the tumorigenesis process through protein-DNA interaction with E2F1 (E2F transcription factor 1) and finally, DDX55 expression is indirectly controlled by SOD2(superoxide dismutase 2, mitochondrial), which is directly involved in neoplasia and carcinogenesis." (PMID 22280244, 2012). "Up-regulation of SOD2 has been suggested as a tumor cells’ escape from oxidative stress." (PMID 22859959, 2012). "Taken together, these data have raised the compelling issue that, in addition to the effects of SOD2 as a guardian against ROS, SOD2 may phenotypically act as a tumour suppressor." (PMID 17895890, 2007). "Also, SOD2 has an important role in tumor development and response to treatment." (PMID 41441336, 2025).
tumor (continued). "Finally, we hypothesize that the genetic damage caused by the collaboration of both factors may favor neoplastic development or favor tumor progression through the positive regulation of SOD2." (PMID 37108069, 2023). "In addition, in vitro experiments confirmed that AFG1 induced high expression of TNF-α and SOD-2 in human macrophage THP-1 (MΦ-THP-1 cells); that is, AFG1 could induce a tumor-associated inflammatory microenvironment." (PMID 37759978, 2023). "In addition, the dose and duration of 1,25(OH)2D in LM7 cells resulted in a maximal 2-fold overexpression of SOD2, a potent antioxidative enzyme that inhibits tumor progression via reduced free radical production, which was less pronounced compared to MG63 cells." (PMID 37228489, 2023). "Furthermore, when this family of proteins was analyzed in non-metastatic stages (I, II, and III), the non-tumor adjacent tissue showed higher levels of antioxidant enzymes, although the tumor tissue presented higher levels of manganese superoxide dismutase (SOD2) and acetylated SOD2." (PMID 36139645, 2022). "Thus, we speculate that the role of SOD2 in protecting against ROS-induced cell death may also holds true for non-tumor cells." (PMID 35667246, 2022). "This may have been due to the different expression levels of SOD2 in different tumor tissues." (PMID 35678690, 2022). "Mitochondrial superoxide dismutase (SOD2) plays an important role in the elimination of mitochondrial ROS, and inhibition of SOD2 activity may lead to oxidative imbalance, increase intracellular ROS, and lead to tumor cell death." (PMID 39070608, 2022). "In our co-expression analysis, SOD2 was found to be one of the genes defining the M2-mesenchymal subtype, which is characterized by poor survival, extensive necrosis, inflammation, angiogenesis, highly cell-enriched tumor micro-environment, and resistance to different therapies." (PMID 35328369, 2022). "Importantly, our results have implications beyond SOD2 inhibition, and suggest that development of clinical compounds targeting mitochondrial ATP production may be a promising approach to sensitize tumor cells to ROS-generating therapies." (PMID 35667246, 2022). "Depending on the type of tumor and its progression, SOD2 may have contrasting effects." (PMID 32111081, 2020). "Bulk RNA-seq analysis of CD1c+CD14+ cells sorted from tumor-invaded lymph nodes indicated that they displayed a similar expression profile as blood DC3s (high expression of cDC2 markers such as CLEC10A and FCER1A combined with low expression of monocyte-associated markers such as C5AR1 and SOD2)." (PMID 32610077, 2020). "Therefore, SOD2 upregulation is critical for tumor progression." (PMID 30755594, 2019). "TrkAIII upregulated SOD2 expression, increased mitochondrial SOD2 activity and attenuated the accumulation of mitochondrial free radical ROS, thereby promoting NB cell line resistance to mitochondrial free radical ROS-mediated death and increasing tumor stem cell-like phenotype." (PMID 31191243, 2019). "However, recent studies have shown that SOD2 exhibits tumor-type dependent function." (PMID 31658599, 2019). "Thus, SOD2 is critical for tumor progression under diverse conditions." (PMID 30755594, 2019). "In addition, SOD2 may be a tumor suppressor, as SOD2 expression has been reported reduced in tumors." (PMID 29677102, 2018). "Besides, SOD2 has also been reported to facilitate tumor metastasis." (PMID 30596106, 2018). "Hence, increased SOD2 expression likely plays a dual role in aiding tumor progression." (PMID 29099803, 2017). "However, unlike true tumor suppressor- or onco-genes, the SOD2 gene is not frequently lost, or rarely mutated or amplified in cancer." (PMID 29099803, 2017).